Y_RNA (Y RNA )
Gene: Miscellaneous RNA gene on chromosome 10 (97,421,195 to 97,421,307, reverse strand). Ensembl gene ENSG00000200737.
Homologues: Paralogues in human: RNY1P5 (91% identical), Y_RNA (88% identical), RNY1 (87% identical), Y_RNA (87% identical), Y_RNA (86% identical), Y_RNA (85% identical), Y_RNA (84% identical), RNY1P1 (83% identical), Y_RNA (83% identical), Y_RNA (82% identical), Y_RNA (81% identical), RNY1P6 (81% identical), and 96 more.